TEAD4 (TEA domain transcription factor 4)
Description:
Transcription factor which plays a key role in the Hippo signaling pathway, a pathway involved in organ size control and tumor suppression by restricting proliferation and promoting apoptosis. The core of this pathway is composed of a kinase cascade wherein MST1/MST2, in complex with its regulatory protein SAV1, phosphorylates and activates LATS1/2 in complex with its regulatory protein MOB1, which in turn phosphorylates and inactivates YAP1 oncoprotein and WWTR1/TAZ. Acts by mediating gene expression of YAP1 and WWTR1/TAZ, thereby regulating cell proliferation, migration and epithelial mesenchymal transition (EMT) induction. Binds specifically and non-cooperatively to the Sph and GT-IIC 'enhansons' (5'-GTGGAATGT-3') and activates transcription. Binds to the M-CAT motif.
Synonyms: RTEF1; TCF13L1; TEF3; TEF-3; TEFR-1; EFTR-2; RTEF-1; hRTEF-1B
Tractability: Small molecule: a structure with a bound ligand is known; a high-quality ligand is known. PROTAC: ubiquitination databases record sites on it; a small molecule that binds it is known.
Target class: Transcription factor
Chemical probes: GNE-7883 (high quality), VT104 (high quality)
Gene: Protein-coding gene on chromosome 12 (2,959,330 to 3,040,676, forward strand). Ensembl gene ENSG00000197905.
Subcellular location: Nucleus
Subcellular location (Human Protein Atlas): Nucleoplasm
Pathways (Reactome):
Developmental Biology: Formation of axial mesoderm; Zygotic genome activation (ZGA)
Gene expression (Transcription): RUNX3 regulates YAP1-mediated transcription; YAP1- and WWTR1 (TAZ)-stimulated gene expression
Immune System: Regulation of PD-L1(CD274) transcription
Gene Ontology:
Molecular function: DNA-binding transcription factor activity; protein binding; DNA-binding transcription factor activity, RNA polymerase II-specific; RNA polymerase II cis-regulatory region sequence-specific DNA binding; DNA binding; DNA-binding transcription activator activity, RNA polymerase II-specific; sequence-specific DNA binding
Biological process: hippo signaling; embryonic organ development; muscle organ development; regulation of transcription by RNA polymerase II; skeletal system development; DNA-templated transcription; positive regulation of DNA-templated transcription; positive regulation of transcription by RNA polymerase II; regulation of DNA-templated transcription
Cellular component: nucleoplasm; nucleus; chromatin; transcription regulator complex; cytoplasm; protein-DNA complex
Genetic constraint (gnomAD): Loss-of-function variants: 36 observed, 53.49 expected, observed/expected ratio (o/e) 0.67, 90% interval 0.51 to 0.89. The upper end of that interval is the gene's LOEUF score, 0.89, which puts it in group 3 of 6, group 1 being the genes least tolerant of losing a copy. Missense variants: 508 observed, 607.29 expected, observed/expected ratio (o/e) 0.84, 90% interval 0.78 to 0.9. Synonymous variants: 220 observed, 240.07 expected, observed/expected ratio (o/e) 0.92, 90% interval 0.82 to 1.02.
Homologues: Orthologues: chimpanzee TEAD4 (99% identical), dog TEAD4 (97% identical), guinea pig TEAD4 (96% identical), pig TEAD4 (96% identical), rat Tead4 (93% identical), mouse Tead4 (92% identical), rabbit TEAD4 (67% identical), Drosophila melanogaster sd (59% identical). Paralogues in human: TEAD1 (74% identical), TEAD3 (69% identical), TEAD2 (64% identical).
Diseases named in the same sentence as TEAD4 in open-access papers:
TEAD4 is named in the same sentence as 92 diseases in open-access papers, as found by Europe PMC text mining. Sharing a sentence is not in itself a finding about the gene and the disease. The quoted sentences say what the papers report.
gastric cancer (29 papers, 2016 to 2025). A primary or metastatic malignant neoplasm involving the stomach. "Hypo-methylation at CpG sites of TEAD4 promoter causing TEAD4 overexpression in gastric cancer tissues resulted in larger tumor size and lower survival rates." (PMID 35602596, 2022). "In addition, TEAD4 was reported to be an oncogenic factor in gastric cancer and to be associated with a poor overall survival rate." (PMID 32678071, 2020). "For instance, TEAD4-activated MNX1-AS1 has been shown to facilitate gastric cancer progression through the EZH2/BTG2 and miR-6785-5p/BCL2 axes." (PMID 39735666, 2025). "TEAD4 plays an oncogenic role in many cancers including gastric cancer, hepatocellular carcinoma, lung adenocarcinoma and head neck squamous cell carcinoma by increasing cancer cell proliferation, migration and epithelial-mesenchymal transition (EMT)." (PMID 35986277, 2022). "Upregulation of TEAD4 has been reported in several cancers, including colon cancer, gastric cancer, breast cancer, and prostate cancer and serves as a valuable prognostic marker." (PMID 35602596, 2022). "In gastric cancer, TEAD4 promotes cell cycle G1/S progression by increasing the expression of cyclins (D1 and E1) and CDKs (CDK2, 4, 6)." (PMID 35602596, 2022). "It should be noted that, both TEAD1 and TEAD4 are overexpressed in gastric cancer TCGA cohort in this study." (PMID 35602596, 2022). "VGLL4-mimicking peptide (super TDU) abrogates YAP binding to TEAD4, which has anti-tumor effects in gastric cancer patient-derived cells and in vivo in the gastric cancer mouse model driven by Helicobacter pylori infection." (PMID 31018586, 2019). "Multiple downstream targets including vimentin and FSCN1 have been identified to mediate EMT induced by TEAD4 in colorectal cancer and gastric cancer." (PMID 30459528, 2018). "TEAD4 stimulates the glycolysis and proliferation of gastric cancer cells." (PMID 39228892, 2024). "By contrast, TEAD4 overexpression is observed in all four gastric cancer types, including additional gnomically stable subtype and chromosomal instability subtype, suggesting TEAD4 may have higher impact on gastric cancer progression." (PMID 35602596, 2022). "Similarly, TEAD4 was previously investigated to facilitate the malignant behaviors of some cancer cells, such as those in gastric cancer, head neck squamous cell carcinoma, and esophageal cancer." (PMID 33517828, 2021). "The transcription factor TEAD4 mediates MNX1-AS1 expression to drive gastric cancer progression." (PMID 34772911, 2021). "This study also demonstrated that MNX1-AS1 could be activated by transcriptional enhancer factor TEF-3 (TEAD4) and then promote gastric cancer progression." (PMID 33093444, 2020). "To further confirm the role of YAP1 in the regulation of AGK in gastric cancer cells, we associated AGK expression with other YAP1‐related proteins in gastric cancer tissue samples and found that AGK expression was also associated with the expression of TEAD1, TEAD2 and TEAD4." (PMID 32827244, 2020). "Previous studies have revealed that TEAD4 is usually amplificated and/or overexpressed in multiple cancers including atypical teratoid/rhabdoid tumor, serous ovarian carcinoma, colorectal cancer, lung adenocarcinoma, gastric cancer and OSCC." (PMID 30459528, 2018). "Thus, we hypothesized that XIST recruits hnRNPK to promote the nuclear translocation of the YAP1 protein and YAP1/TEAD4-mediated VEGFA transcription in gastric cancer cells." (PMID 40860183, 2025). "MNX1-AS1 activated by TEAD4 can promote the GC process through EZH2/BTG2 and miR-6785-5p/BCL2 axes, suggesting that it was a novel and effective therapeutic target for gastric cancer." (PMID 34712264, 2021). "As de-methylation at enhancers is often associated with the binding of transcription factors during carcinogenesis, we investigated whether those hypo-methylated enhancers were bound by TEAD4 by analyzing the previously published TEAD4 ChIP-seq data in two gastric cancer cell lines." (PMID 27016420, 2016).
gastric cancer (continued). "TEAD4 is TEA domain-containing transcription factor, which is frequently overexpressed in diverse cancers, including ovarian, liver, colorectal, and gastric cancers." (PMID 39735666, 2025). "The regulatory function of TEAD4, ETV4, PRRX1, and FOXM1, over other key TFs and common DEGs, was highlighted in gastric cancer, establishing key co-regulatory complexes." (PMID 39228892, 2024). "TEAD4 is one of the important member of the TEAD family, and was reported to be a innovate prognostic marker in many cancer which includes gastric cancer, breast cancer, colorectal cancer, melanoma." (PMID 35794546, 2022). "In gastric cancer, we confirmed that VGLL1, which has a similar structure to TAZ, binds with TEAD4 to the integrin αV promoter in the presence of TNF-α." (PMID 36613819, 2022). "A study found that TEAD4 bound to the promoter of LncRNA MNX1-AS1 to induce its transcription, thereby implicating in the progression of gastric cancer." (PMID 33517828, 2021). "Moreover, these virus-induced signals increase the expression of IRF3 (Interferon Regulatory Factor 3), a key regulator of innate immunity, which binds to YAP/TEAD4 complex and upregulates YAP target genes in gastric cancer." (PMID 35602596, 2022).
breast carcinoma (28 papers, 2015 to 2025). "The bioinformatic analysis from the TCGA database suggested that high levels of TEAD4 mRNA are associated with metastasis and recurrence of breast cancer patients." (PMID 25970772, 2015). "High expression levels of TEAD4 mRNA are significantly associated with distant metastasis and recurrence of breast cancer patients." (PMID 25970772, 2015). "In the context of breast cancer, TEAD4 functions as a key effector of the Hippo signaling pathway, a critical regulator of organ size, cell proliferation, and apoptosis." (PMID 40862714, 2025). "NFE2 can confer growth advantages on breast cancer cells under hypoxia and anchorage‐independent conditions, while TEAD4 expression is the most frequently observed among the four TEAD members in various types of cancers." (PMID 38501838, 2024). "Consistent with the clinic data, we found that siRNA-mediated depletion of TEAD4 downregulated ERα target gene expression and inhibited ER+ breast cancer cell growth." (PMID 35654829, 2022). "In this study, we report that YAP1, which interacts with the transcription factor TEAD4, induces invadopodia formation and promotes tumor metastasis in breast cancer cells." (PMID 35773411, 2022). "The tyrosine protein kinase, MET, induces phosphorylation of β-catenin which binds and translocates YAP into nucleus to form a transcriptional complex with TEAD4 in breast cancer." (PMID 35602596, 2022). "TEAD4 expression correlates not only positively with GR expression in breast cancer, but also with poor survival and metastasis." (PMID 35602596, 2022). "It was reported that glucocorticoid-activated TEAD4 promoted maintenance, metastasis, and chemoresistance of breast cancer stem cells, high expression of TEAD4 predicted a poor outcome in breast cancer patients." (PMID 35739490, 2022). "While TEAD4 activation by GC promoted breast cancer stem cell maintenance, cell survival, metastasis, and chemoresistance both in vitro and in vivo, it was also completely blocked by cotreatment with mifepristone." (PMID 35761157, 2022). "We found that, in different types of cells (A549-lung cancer, H1-human embryonic stem cells, HCT-116-colon cancer, MCF-7-breast cancer, SK-N-SH-neuroblastoma), TEAD4 directly binds to the promoter regions of RAD51C gene." (PMID 34488828, 2021). "TEAD4 is already a known biomarker for breast cancer, colorectal cancer and prostate cancer; its TF binding motif regions are hypomethylated in CCA." (PMID 33193605, 2020). "TEAD4 was found overexpressed in breast cancer to induce cell proliferation and tumor growth by inhibiting p27 transcription." (PMID 29050244, 2017). "Here we found that TEAD4 was expressed in breast cancer cell lines, especially in triple negative breast cancers (TNBC) cell lines." (PMID 25970772, 2015). "Among four members of TEAD, TEAD1 and TEAD4 are widely expressed in breast cancer cell lines, especially highly expressed in TNBC cell lines." (PMID 25970772, 2015). "TEAD4 is a potential target and biomarker for the development of novel therapeutics for breast cancer." (PMID 25970772, 2015). "Additionally, we suggest a relation between the transcription factor TEAD4 and lnc-uc.147 in liver and breast cancer cells." (PMID 36830634, 2023). "In addition, glucocorticoids promote breast cancer cell resistance to cytotoxic compounds like taxanes during cancer treatment through the interaction between GRs and TEA domain transcription factor 4 (TEAD4)." (PMID 36707854, 2023). "TEAD4 acts as an oncogene in breast cancer, and its high expression predicts poor survival." (PMID 35761157, 2022). "Nuclear YAP could interact with β-catenin and TEAD4 at gene regulatory elements to promote basal-like breast cancer formation, luminal to basal trans-differentiation and the acquisition of CSCs-related properties." (PMID 35064101, 2022).
breast carcinoma (continued). "Among the different members of the TEAD family, TEAD4 has been previously shown to be up-regulated in breast cancer cell lines (and in particular in TNBC) and to be able to control the expression of genes involved in breast cancer cell migration and invasion like HMMR." (PMID 28978043, 2017). "YAP, TAZ and TEAD4 are well-known regulators of breast cancer cell migration and invasion." (PMID 28978043, 2017). "Therefore, we were surprised to find that high levels of TEAD4 correlated with poor prognosis in ER+ breast cancer patients, which is in contrast to YAP, implying that TEAD may promote ER+ breast cancer progression." (PMID 35654829, 2022). "Receptor tyrosine kinase EPHR activated in breast cancer upregulates YAP/TAZ expression and increases YAP accumulation and the expression of YAP/TEAD4 target genes." (PMID 35602596, 2022). "YAP1 and TEAD4 can also recruit mediator complex subunit 1 (MED1), an important enhancer activating machinery, to facilitate breast cancer cell growth." (PMID 35883668, 2022). "Another coactivator of TEAD4 is glucocorticoid receptor which binds TEAD4 and acts, in a YAP-independent manner, to promote transcription in breast cancer." (PMID 35602596, 2022). "Proximity labeling techniques in MCF7 breast cancer cell lines have identified YAP and TEAD4 as cofactors for ERα/FOXA1 on active estrogen-regulated enhancers." (PMID 35883668, 2022). "While a variety of studies have identified roles for other Wnt signaling factors in basal-like breast cancer, few exist for WNT5B and TEAD4." (PMID 30484104, 2019). "In this study, we investigated the expression and roles of TEADs in breast cancer and found that TEAD1 and TEAD4 are widely expressed in several breast cancer cell lines, particularly TNBC lines." (PMID 25970772, 2015). "Similarly, in breast cancer, TEA domain transcription factor 4 (TEAD4) binds to the GLUT3 promoter, increasing its expression and thereby contributing to PTX chemoresistance." (PMID 40264038, 2025). "Interestingly, in breast cancer, the complex between YAP1/TEAD4 can bind to enhancer regions of the estrogen receptor gene, causing an increase in the proliferation of estrogen-responsive breast cells." (PMID 36830634, 2023). "In fact, both TEAD4 and TAZ over-expression in breast cancer correlates with poor prognosis." (PMID 28978043, 2017). "Similarly to GTSE1, HMMR is regulated by both TEAD4 and E2F1 and has a critical role in breast cancer cell migration." (PMID 28978043, 2017). "Our examination showed that both TEAD1 and TEAD4 are widely expressed in breast cell lines, though the expression levels were higher in two basal immortalized breast epithelial cell lines and two basal TNBC cell lines as compared to ERα+ or HER-2+ breast cancer cell lines." (PMID 25970772, 2015). "Our previous studies showed that KLF5 promotes breast cancer cell proliferation, survival and tumor growth, but whether or not TEAD4 has similar functions is not entirely clear." (PMID 25970772, 2015). "Moreover, we found that TEAD4 controls the formation of cell protrusions required for cell migration through GTSE1, unveiling a relevant effector role for this protein in the TEAD-dependent cellular functions and confirming TEAD4 role in promoting invasion and metastasis in breast cancer." (PMID 28978043, 2017). "Public bioinformatics analysis showed that TEAD4, rather than TEAD1-3, was dramatically transcribed among the TEADs family members and was positively correlated with poor prognosis in patients with breast cancer." (PMID 35773411, 2022).
colorectal cancer (16 papers, 2017 to 2025). A primary or metastatic malignant neoplasm that affects the colon or rectum. "Mechanistically, this is due to the formation of complexes between Yap/TAZ and TEAD4 in both colorectal cancer cells and cancer-associated fibroblasts, which directly enhance CCBE1 transcription through interaction with its enhancer regions." (PMID 40806273, 2025). "For example, elevated TEAD4 expression significantly associated with advanced stage, distant metastasis and poor outcome in colorectal cancer." (PMID 30459528, 2018). "In colorectal carcinoma, TEAD4 nuclear localization and regulation was demonstrated using miR-4269 and miR-1343-3p." (PMID 39039559, 2024). "TEAD4’s nuclear expression can be used as a biomarker for colorectal cancer progression and poor prognosis." (PMID 35602596, 2022). "Remarkably, it has been shown that in colorectal cancer cells TEAD4 promotes EMT in a YAP independent manner, regulating the expression of Vimentin." (PMID 36186582, 2022). "It appears that the TEAD4-regulated transcriptome in colorectal cancer is also rich in genes that contribute to colon cancer recurrence." (PMID 30400241, 2018). "Higher levels of TEAD2 and TEAD4 were also found in colorectal cancer, specifically in metastatic tissues, and experiments performed in vivo and in vitro have shown that knockdown of TEAD4 reduces metastasis and cell migration." (PMID 30513609, 2018). "In colorectal cancer, TEAD4 targets EMT genes and promotes metastasis." (PMID 35602596, 2022). "Similarly, the overexpression of TEAD4 direct target gene SIX1 (sine oculis 1) correlates with poor prognosis of colorectal cancer patients." (PMID 35602596, 2022). "Moreover, in colorectal cancer cells TEAD4 directly enhances the expression of Vimentin." (PMID 36186582, 2022). "In colorectal cancer, YAP/TEAD4 cooperates with AP-1 and the p160 family of steroid receptor coactivator SRC1-3 to regulate the genes associated with tumor migration and invasion." (PMID 35602596, 2022). "TEAD4 regulates epithelial-to-mesenchymal transition and metastasis in a YAP-independent manner in colorectal cancer." (PMID 32637580, 2020). "Also, a recent study described a link between Bcl-2 and YAP, demonstrating that TEAD4 binds to the promoter regions of Bcl-2 and that YAP silencing abrogated downregulated Bcl-2 protein in colorectal cancer cells." (PMID 38755629, 2024). "In addition, increased nuclear TEAD4 expression promoted EMT and metastasis in colorectal cancer while its knockdown induced mesenchymal-epithelial transition and decreased cell mobility in vitro and metastasis in vivo." (PMID 30459528, 2018).